ACAT2 (acetyl-CoA acetyltransferase 2)
Diseases named in the same sentence as ACAT2 in open-access papers (continued):
Sharing a sentence is not in itself a finding about the gene and the disease.
tumor (22 papers, 2019 to 2026). "As proven above, increased ACAT2 expression was associated with large tumour size and advanced pN stage." (PMID 38670954, 2024). "Clinicopathological data analysis of GC patients from our hospital indicated that the high expression of ACAT2 was closely associated with later pN stage, larger tumour size and lower survival rate." (PMID 38670954, 2024). "Our model predicts that Acetoacetyl-CoA Synthetase (AACS) depletion is selectively lethal to malignant cells because the alternative route for Acetoacetate-CoA synthesis, Acetyl-CoA Acetyltransferase 2 (ACAT2) is selectively depleted in the tumor region." (PMID 32103057, 2020). "Then, we further conducted Kyoto Encyclopedia of Genes and Genomes (KEGG) pathway enrichment analysis based on the RNA-seq data (GSE246567) and found that multiple tumour-related pathways were activated, among which the Hippo signalling pathway was the most affected one by ACAT2 deficiency." (PMID 38670954, 2024). "Among the mechanisms, one may highlight the JAK2/STAT3 signaling pathway, the activation of the extracellular-signal-regulated kinase (ERK) pathway, the upregulation of acetyl-CoA acetyltransferase 2 (ACAT2), and the induction of IL-8 expression in tumor-associated macrophages (TAMs)." (PMID 40485730, 2025). "THIC/ACAT2, another protein inversely correlated with tumor size, is involved in the cholesterol biosynthesis pathway." (PMID 41441336, 2025). "Histological analysis demonstrated that knockdown of CAPZA1 significantly inhibited tumor cell proliferation, lipid deposition, and ACAT2 expression in xenograft tumors, whereas OSS-128167 treatment further enhanced these inhibitory effects." (PMID 41354870, 2025). "While ACAT2 has limited value in tumors, ACAT1 has been found to be implicated in tumor occurrence and development." (PMID 38720812, 2024). "ACAT1 is widely expressed in multiple tumor types, while ACAT2 is predominantly distributed in some organs, like small intestine and liver." (PMID 38213102, 2024). "Previous studies demonstrated that ACAT2 either promotes or suppresses tumor progression in different conditions." (PMID 38670954, 2024). "There was a significant correlation between the expression of ACAT2 and tumor staging pathological stage." (PMID 38213102, 2024). "Tumor tissues had significantly higher expression levels of ACAT2, when compared to normal adjacent tissues." (PMID 38213102, 2024). "It has been shown that ACAT2 was induced in some HCC tissues to establish specific cholesterol metabolic pathways for tumor cells, which in turn inhibits anti-tumor immunity." (PMID 38755125, 2024). "In our study, to compare with the ACAT2 mRNA expression levels in tumor and normal tissues, The Cancer Genome Atlas (TCGA) program and Xiantao bioinformatics tool were performed." (PMID 38213102, 2024). "There was high correlation between the expression of ACAT2 and fourteen tumor functional statuses in the heatmap." (PMID 38213102, 2024). "We used the GEPIA2 tool to explore the relationship between the expression of ACAT2 and tumor pathological stage." (PMID 38213102, 2024). "Collectively, these findings demonstrate that ACAT2 contributes to the proliferation of GC cells in vitro and tumour growth in vivo." (PMID 38670954, 2024). "The GEPIA database was utilized to analyze the correlation between ACAT2 expression and pathological stage of the tumor." (PMID 38213102, 2024). "While in Zhao’s research, high-expressed ACAT2 was related to early tumor stage and longer survival, which was contradicted with ours." (PMID 38178203, 2024). "Taking the in vitro and in vivo results together, it was shown that Txnip, Aox1, Per3 and Ypel3 were consistently upregulated in both tumor lines and Acat2, Clspn and Ercc6l were downregulated." (PMID 33407762, 2021). "Knockdown of ACAT2 resulted in decreased lysine acetylation of 6PGD, then blunted tumor growth." (PMID 38213102, 2024).
tumor (continued). "Moreover, IHC confirmed that ACAT2-depleted NCI-N87 tumour masses manifested significantly weaker Ki-67 staining than the tumour masses derived from the control cells." (PMID 38670954, 2024). "Therefore, the expression of Il6, Nos2, Ccl2, Spp1, Tnf, Acat2, Aox1, Crem, Gls2, Per3, Pink1, Txnip, and Ypel3 was examined in acidosis upon simultaneous transfection with microRNA mimics or antagomirs in two tumor lines in vitro and in vivo." (PMID 38069241, 2023). "In addition, ACAT1 and ACAT2 were both significantly higher in compact than clear tumor cells, suggesting that they were in equilibrium with cholesterol ester metabolism to maintain the homeostasis of intracellular free cholesterol levels." (PMID 35216289, 2022). "It has also been proposed that PLAGL1 protein levels in CCRCC tissues are positively correlated with distant metastasis and worse patient prognosis; the ACAT2 gene was related to lipid metabolism, and its downregulation could lead to a poor tumor-specific survival prognosis." (PMID 38730456, 2024). "While all proteins, as expected, were correlated with tumor stage according to proteomic data, GANAB, THIC/ACAT2, SEPT8, PPIA, and GALE showed an inverse correlation with tumor size, whereas MYDGF displayed a positive correlation." (PMID 41441336, 2025). "As a result of reduced ACAT2 expression in NCI-N87 cells, the growth rate was significantly decreased, as was the weight of the harvested tumour mass." (PMID 38670954, 2024). "The MREs ACAT1, ACAT2, FDFT1, FDPS, HMGCL and PMVK were highly expressed in basal tumor cells and urothelial cells." (PMID 39521858, 2024). "As a result of reduced ACAT2 expression in HGC-27 cells, the number of metastases was significantly decreased, as was the weight of the harvested tumour mass." (PMID 38670954, 2024). "Membranous immunoreactivity of SR-B1 (p = 0.0289), and cytoplasmic immunoreactivity of ACAT1 (p = 0.0004), ACAT2 (p < 0.0001), HSL (p < 0.0001) and DHCR24 (p < 0.0001) were significantly higher in compact than in clear tumor cells." (PMID 35216289, 2022). "K294 acetylation in 6-phosphogluconate dehydrogenase (6-PGD) was regulated by ACAT2, which was related to NADPH production and tumor growth." (PMID 34664012, 2021). "Our findings elucidate the mechanisms underlying the role of SIRT6 in ccRCC by identifying an endogenous metabolite, LPE18:1, as a novel upstream activator of SIRT6 and by elucidating ACAT2 as a key downstream effector responsible for SIRT6-mediated lipid accumulation and tumor progression." (PMID 41354870, 2025). "ACAT2 and SPHK1 were related to lipid metabolism and some tumor-promoting pathways, SNED1 might be related to cell matrix adhesion." (PMID 37202800, 2023).
infection (7 papers, 2012 to 2025). The state of being infected such as from the introduction of a foreign agent such as serum, vaccine, antigenic substance or organism. "Compared to mock-infected cells at day 1 post-infection, C. burnetii infection upregulated the expression of genes acat-1, acat-2, fabp-4 and apoE by more than 1.2 fold." (PMID 29390006, 2018). "Similar to H19 overexpression though, silencing H19 expression also up‐regulated most of the genes involved in lipid breakdown, such as Acat2, Cpt1b, Ndafs4, Pck2, Cyp1a2, Acads and Atpsa1, at 72 hours after Ad‐H19 infection, although most of them were down‐regulated at 36 hours after infection." (PMID 31809000, 2020). "Besides, PPARγ, some of the critical enzymes involved in fatty acid biosynthesis, TAG biosynthesis, cholesterol esterification like Fasn, Dgat1, Dgat2, Mgat1, Acat1, Acat2, etc., showed a temporal increase in expression levels at the later time points post-infection." (PMID 41358489, 2025). "Three genes involved in the synthesis of acetyl CoA, AACS (2.0 fold), ACAT2 (3.5 fold) and ACLY (2.2 fold) were up-regulated by infection; however, this compound and it precursors or metabolites were largely unaltered by infection." (PMID 32732949, 2020). "Infection of cells overexpressing wild-type ACAT2, but not ACAT1, resulted in a significant increase in viral RNA and infectious particles." (PMID 37134108, 2023).
metabolic disorders (2 papers, 2023 to 2025). "For instance, in subclinical ketosis, downregulation of acetyl-CoA acetyltransferase 2 (ACAT2) (a CoA-dependent enzyme) leads to hepatic triglyceride accumulation and impaired cholesterol synthesis, underscoring how CoA-related molecular events drive metabolic disorders." (PMID 41359645, 2025).
cardiac disease (1 paper, 2008). "While elevated levels of apoB and reduced levels of apoA1 are associated with increased cardiac disease, serum levels of apoB100 associated VLDL are regulated in turn by Acat2 which stimulates cholesteryl ester secretion into apoB-containing lipoproteins." (PMID 18959802, 2008).
ACAT2 also shares sentences with these, for which no sentence is quoted: type 2 diabetes (3 papers); coronary heart disease (2); hepatocellular carcinoma (2); arrhythmogenic right ventricular cardiomyopathy (1); breast tumors (1); depression (1); diabetes mellitus type 2 (1); dilated cardiomyopathy (1); Ductal Carcinoma (1); epilepsy (1); galactosialidosis (1); Glucose intolerance (1); Granuloma (1); Hypertension (1); hypertriglyceridemia (1); hypertrophic cardiomyopathy (1); kidney cancer (1); lipid metabolism disorders (1); lung adenocarcinoma (1); Mucolipidosis III gamma (1); neural tube defect (1); nicotine dependence (1); prostate carcinoma (1); Renal insufficiency (1); Sandhoff disease (1); serous carcinoma (1).